RNU6-319P (RNA, U6 small nuclear 319, pseudogene)
Gene: Small nuclear RNA gene on chromosome 9 (15,431,899 to 15,432,006, reverse strand). Ensembl gene ENSG00000251834.
Homologues: Orthologues: chimpanzee U6 (99% identical), macaque U6 (93% identical), dog U6 (71% identical), rat LOC120093900 (69% identical), guinea pig U6 (62% identical). Paralogues in human: RNU6-115P (70% identical), RNU6-242P (69% identical), RNU6-1094P (69% identical), RNU6-1159P (69% identical), RNU6-1216P (69% identical), RNU6-727P (69% identical), RNU6-1091P (68% identical), RNU6-169P (68% identical), RNU6-485P (68% identical), RNU6-668P (68% identical), RNU6-1309P (67% identical), RNU6-1329P (67% identical), and 1285 more.